CDC42EP2 (CDC42 effector protein 2)
Description:
Probably involved in the organization of the actin cytoskeleton. May act downstream of CDC42 to induce actin filament assembly leading to cell shape changes. Induces pseudopodia formation in fibroblasts in a CDC42-dependent manner.
Synonyms: BORG1; CEP2
Tractability: Antibody: UniProt places it where antibodies can reach, with high confidence; its Gene Ontology location is reachable by antibodies, with high confidence.
Gene: Protein-coding gene on chromosome 11 (65,314,834 to 65,322,662, forward strand). Ensembl gene ENSG00000149798.
Subcellular location: Endomembrane system; Cytoplasm, cytoskeleton
Subcellular location (Human Protein Atlas): Cytosol; Microtubules; Vesicles
Pathways (Reactome):
Signal Transduction: CDC42 GTPase cycle; MAPK6/MAPK4 signaling; RHOQ GTPase cycle
Gene Ontology:
Molecular function: GTPase activator activity; protein binding; small GTPase binding; opioid peptide activity
Biological process: actin cytoskeleton organization; positive regulation of actin filament polymerization; positive regulation of pseudopodium assembly; regulation of cell shape; actin filament organization; positive regulation of protein-containing complex assembly; Rho protein signal transduction
Cellular component: cytoplasm; membrane; microtubule cytoskeleton; plasma membrane; cytoskeleton; cytosol; endomembrane system; phagocytic vesicle
Genetic constraint (gnomAD): Loss-of-function variants: 5 observed, 7.66 expected, observed/expected ratio (o/e) 0.65, 90% interval 0.34 to 1.36. That is too few expected variants to judge how well the gene tolerates losing a copy. Missense variants: 251 observed, 295.54 expected, observed/expected ratio (o/e) 0.85, 90% interval 0.76 to 0.94. Synonymous variants: 113 observed, 130.51 expected, observed/expected ratio (o/e) 0.87, 90% interval 0.74 to 1.01.
Homologues: Orthologues: chimpanzee CDC42EP2 (99% identical), dog CDC42EP2 (92% identical), pig CDC42EP2 (92% identical), guinea pig CDC42EP2 (91% identical), rabbit CDC42EP2 (89% identical), mouse Cdc42ep2 (89% identical), rat Cdc42ep2 (87% identical), zebrafish cdc42ep2 (61% identical), tropical clawed frog cdc42ep2 (55% identical). Paralogues in human: CDC42EP3 (46% identical), CDC42EP4 (31% identical), CDC42EP1 (29% identical), CDC42EP5 (23% identical), C15orf62 (15% identical).
Diseases named in the same sentence as CDC42EP2 in open-access papers:
CDC42EP2 is named in the same sentence as 12 diseases in open-access papers, as found by Europe PMC text mining. Sharing a sentence is not in itself a finding about the gene and the disease. The quoted sentences say what the papers report.
congenital glaucoma (1 paper, 2024). "The gene ontologies for list 7+ linked the non-overlapping genes CDC42EP2, CLDN5, CNN1, DES, KCNMB1, and MYH11 to Congenital Glaucoma." (PMID 39480826, 2024).
Ehlers-Danlos syndrome (1 paper, 2024). The Ehlers–Danlos syndromes (EDS) are a clinically and genetically heterogeneous group of heritable connective tissue disorders (HCTDs) characterized by joint hypermobility, skin hyperextensibility, and tissue fragility. "The gene ontologies for list 8+ linked CDC42EP2, FOXF1, SGCA, and SORBS1 to Megacystis-Microcolon-Intestinal Hypoperistalsis Syndrome while CDC42EP2 and CNN1 linked to Classical-like Ehlers-Danlos Syndrome." (PMID 39480826, 2024). "No direct link between CNN1 or CDC42EP2 could be made with TNXB or Classical-like Ehlers-Danlos Syndrome (cEDS) through a literature search." (PMID 39480826, 2024).
gastric cancer (1 paper, 2010). A primary or metastatic malignant neoplasm involving the stomach. "For example, ENC-1, often over-expressed in some types of leukemia, KLF12, a transcription factor associated with progression of gastric cancer, and CDC42EP2, a small Rho GTPase binding protein involved in hypoxia-induced angiogenesis, were induced by gefitinib at 24 h treatment." (PMID 20579378, 2010).
Megacystis (1 paper, 2024). Dilatation of the bladder postnatally. "We propose that CDC42EP2, FOXF1, SGCA, and SORBS1 are novel genes in Megacystis-Microcolon-Intestinal Hypoperistalsis Syndrome." (PMID 39480826, 2024).
neuroblastoma (1 paper, 2024). Neuroblastoma (NB) is the most common solid, extracranial childhood tumor. "Our study revealed that the overexpression of WT and A53T α-syn in SK-N-SH neuroblastoma cells caused neurite outgrowth accompanied by increased levels of Cdc42EP2 expression." (PMID 39851377, 2024).
tumor (2 papers, 2020 to 2026). "Among these genes, EFNA4 and TEDC2 were significantly upregulated, whereas CDC42EP2, STX11, THBD, TMEM88, and GPM6A were notably downregulated in tumor tissues compared with adjacent normal tissues." (PMID 42196266, 2026). "KALRN, MCF2/Dbl, NGEF/EPHEXIN, ARHGEF7/βPix/COOL-1, CDC42EP2, DOCK9, NET1, TIAM2, ABR, PLEKHG5, RhoBTB2 and PREX1 were identified as being increased at the tumour rim." (PMID 33256106, 2020).
infection (1 paper, 2015). The state of being infected such as from the introduction of a foreign agent such as serum, vaccine, antigenic substance or organism. "GSEA at 24 h indicated that genes involved in infection, TLR, chemokine and cytokine signaling are enriched as before, but genes involved in phagocytosis are also enriched, including Vav1, Sirpa, Cdc42se1, Cdc42ep2, Fcgr2b/3, and Coro1a." (PMID 25888408, 2015).
CDC42EP2 also shares sentences with these, for which no sentence is quoted: acute myeloid leukemia (1 paper); breast carcinoma (1); leukemia (1); melanoma (1); Obesity (1).